MMP9 (matrix metallopeptidase 9)
Diseases named in the same sentence as MMP9 in open-access papers (continued):
Sharing a sentence is not in itself a finding about the gene and the disease.
tumor (continued). "Immunohistochemistry showed that IR-induced IL-4 increased the expression of major components related to p-Stat6, mesenchymal trait marker, Vimentin; invasiveness marker, MMP-9; stemness maintenance marker, Sox2; and tumor proliferation marker, Ki-67." (PMID 27895317, 2016). "Increased activity of MMP2 and MMP9 seems to play a key role in the growth and invasion of tumor and its metastasis." (PMID 27110571, 2016). "Among MMPs family, MMP2 and MMP9 have been confirmed playing important role in enhancement of tumor metastasis." (PMID 26701209, 2016). "We also determined that the presence of MMP-9 in the tumor/macrophage microenvironment indirectly increased tumor cell proliferation." (PMID 27888810, 2016). "Since MMP14 is an activator of MMP2 and MMP9, a possible mechanism driving tumor invasion and migration is the activation of MMP2 and MMP9 through IL-6 induced MMP14." (PMID 27613828, 2016). "A sequence in the hemopexin domain of MMP-9 (PEX9) impairs tumor cell adhesion to PEX9/MMP9 through interaction with CD44." (PMID 26869928, 2016). "Inflammatory cells surrounding BCC are typically positive for MMP-13, MMP-1, and MMP-9, indicating an essential role of inflammation in modulating tumor progression." (PMID 27271600, 2016). "This is the first to demonstrate that macrophage AEG-1 promotes tumor invasion through up-regulation of MMP-9 in both macrophages and cancer cells." (PMID 27793010, 2016). "A reduction in tumor growth and vascularization has been observed after transplantation of tumor cells into either MMP2 or MMP9 deficient mice, compared to wild-type mice." (PMID 26979530, 2016). "Tissues were analyzed for matrix metalloproteinase 9 (MMP9), an enzyme responsible for the breakdown of extracellular matrix and increase in tumor invasion." (PMID 26871599, 2016). "We found that uc.8+ acts as a decoy for miR-596, inducing the upregulation of its targets, including MMP9, which supports previous findings that miR-596 is a tumor suppressor involved in regulating MMP9." (PMID 26943042, 2016). "MMP-2 and MMP-9 play important roles in the degradation of the extracellular matrix and basement membrane, promoting tumor invasion and metastasis." (PMID 27152521, 2016). "We noted positive expression of MMP-9 in the cytoplasm of tumor cells and in the stroma of patients with PDAC." (PMID 27429508, 2016). "Both metalloproteinases (MMP-2and MMP-9) and type IV collagen are involved in angiogenesis, which is vital for tumor growth and invasion." (PMID 27406386, 2016). "As MMPs, particularly MMP-2 and MMP-9, are necessary for tumor angiogenesis and Activin A has been characterized as a potent inhibitor of this process, we next examined the effect of Activin A overexpressing cultures on endothelial tube formation." (PMID 27829391, 2016). "Here we found that MMP-9 mRNA and protein expressions in tumor tissues were significantly decreased following POC treatment as compared to the other treatment and control group." (PMID 27825139, 2016). "Together, our data showed the infiltrated mast cells in the tumor microenvironment enhance BCa metastasis via stimulating ERβ/CCL2/CCR2 EMT/MMP9 signals both in vitro and in vivo." (PMID 26556868, 2016). "The results (row 2) indicate increased MMP9 in vehicle treated tumor tissues as compared to clorgyline or NMI-treated animals." (PMID 26871599, 2016). "Like other proteases in the MMP family, MMP9 is involved in the degradation of collagen IV in the basement membrane and extracellular matrix and facilitates tumor progression, including invasion and metastasis." (PMID 26943042, 2016). "Neutrophil-derived MMPs, in particular MMP9, have been shown to be the most important activator in tumor vascularization." (PMID 27549025, 2016). "The ground behind these assumptions were paradoxical effect of MMP-9 which demonstrated that reduction of plasma levels of MMP-9 leads to decreased angiostatin synthesis and subsequent increased tumor growth and vascularization." (PMID 26998758, 2016).
tumor (continued). "The primary tumour induces the production of MMP-9 in endothelial cells and macrophages in the lungs via a mechanism dependant on VEGFR-1/FLT-1 tyrosine kinase (TK) that promote metastasis." (PMID 26913068, 2016). "This binding activates p38 and pERK signaling and the expression of the downstream target genes DKK1 and MMP-9, and promotes MM progression by inducing tumor cell spread and ECs invasion." (PMID 27474171, 2016). "Immunohistochemical assessment of MMP-9 in patients with PDAC showed the protein presence in tumor cells in 44.83% of cases and its absence in normal pancreatic ducts and stroma (100% and 75.87%, resp)." (PMID 27429508, 2016). "Recently, OV has been shown to inhibit migration and invasion of MDA-MB-231 and MCF-7 breast cancer cell lines by a decreased matrix metallopeptidase 9 activity, revealing the repression role of OV in tumor metastasis." (PMID 27242913, 2016). "The authors finally concluded that MMP9-cleaved BGH3 plays a crucial role in MMP9-mediated tumor migration." (PMID 26745629, 2016). "MMP2 and MMP9 are secreted into the extracellular space, but they can also become localized at the surface of tumor cells." (PMID 27042827, 2016). "Experiments performed with WT of MMP9-KO mice demonstrated that the tumor vasculature developing in MMP9-KO was represented mainly by collapsed capillaries." (PMID 27618112, 2016). "MMP9 is responsible for formation of leaky vasculature in the pre-metastatic lung and supports tumor cells survival in this organ." (PMID 28066438, 2016). "Statistical analysis confirmed that the positive expression of MMP-9 only in the tumor cells showed a growing tendency in MVD." (PMID 27429508, 2016). "These granulocytic MDSCs (and not monocytic MDSCs) infiltrate the lung premetastatic niche well before tumor cells arrive there and secrete in situ large amounts of MMP-9, resulting in aberrant and leaky vasculature in the premetastatic lung." (PMID 26997761, 2016). "Especially MMP-9 has been related to tumor aggressiveness in different tumor types, including sarcomas." (PMID 27487136, 2016). "MMP-2 and MMP-9 cleave type IV collagen, the major structural protein for ECM and basement membrane and are consequently associated with tumor development." (PMID 25888629, 2015). "Gelatinases such as MMP-2 and MMP-9 play a crucial role in tumor cell aggressiveness such as invasion and metastasis." (PMID 26608825, 2015). "In the present study, we found that MMP9 was down-regulated in luteolin-treated tumor tissue and cancer cells." (PMID 25638174, 2015). "RECK suppresses tumor invasion by negatively regulating at least three members of the matrix metalloproteinase family: MMP-9, MMP-2, and MT1-MMP." (PMID 26431549, 2015). "Tumor MMP-9 expression correlated with relapse in operable NSCLC patients; however, we were not able to demonstrate the clinical significance of tumor MMP-9 expression as a prognostic marker for relapse and survival." (PMID 25888323, 2015). "Others argue that it’s involved in regulating other receptor protein expression-SPARC and MMP9 interact to regulate tumor metastasis.and controlling vascular formation." (PMID 26674531, 2015). "In contrast, blocking RhoA activity significantly inhibits MMP2 and MMP9 expression, tumor invasion, and lung metastasis." (PMID 25889562, 2015). "In HNSCC, expression of MMP-9 was larger by TANs than by any other cell type in the tumor, and in hepatocellular carcinoma larger numbers of TANs correlated with more angiogenesis." (PMID 26819959, 2015). "Occurrence of relapse (21.9% vs. 36.0%; p = 0.002) and death (34.8% vs. 37.9%; p = 0.518) was higher among patients with tumor MMP-9 expression." (PMID 25888323, 2015). "A number of genes that are linked to NF-κB, including MMP-9, VEGF, cyclin-D1, Bcl-2, and XIAP, contribute to the development of tumor radioresistance." (PMID 26539482, 2015).
tumor (continued). "Various pathological processes such as tumor invasion, atherosclerosis, inflammation, and rheumatoid arthritis can stimulate MMP-9 synthesis and secretion, whereas MMP-2 is usually constitutively overexpressed." (PMID 25670016, 2015). "Most importantly, we also show a strong correlation of TSP50 and MMP9 coexpression with the patient tumor metastasis." (PMID 25811800, 2015). "Reconstitution of tumor-bearing MMP-9−/− mice with wild type, MMP-9-competent hematopoietic cells demonstrated that tumor-infiltrating myeloid cells were the source for MMP-9." (PMID 26819959, 2015). "MMP-9 is known to be a key factor in the degradation of the extracellular matrix and angiogenesis, processes related to tumor metastasis." (PMID 25888323, 2015). "Further, it is noteworthy that the ratio of active to latent forms of MMP-9 increases with tumor progression in invasive cancers." (PMID 25830682, 2015). "IHC staining showed higher TR4 level, more macrophage infiltration, lower TIMP-1 and stronger MMP2/MMP9 in tumor tissues of the Gleason score 5 + 4 patients compared with the Gleason score 3 + 3 patients." (PMID 25623427, 2015). "In tumor biology, it has been increasingly appreciated that MMP-9 from inflammatory cells, particularly neutrophils, codetermines prognosis and outcome." (PMID 26425658, 2015). "The LMVD assays and the assessment of VEGF-C and MMP-9 expression demonstrated relationships between lymphangiogenesis and tumor invasiveness with tumor clinicopathological parameters." (PMID 26656588, 2015). "MMP9 belongs to a large family of proteases that play important roles in degrading the extracellular matrix thereby facilitating tumor invasion." (PMID 26700636, 2015). "N-acetyl cysteine and selenium have been demonstrated to inhibit tumor cell MMP-9 and invasive activities, as well as the migration of endothelial cells through the ECM." (PMID 25574189, 2015). "The inhibition of protein expressions related to the cell proliferation (cyclin D1) and tumor invasion (MMP-9 and RANKL) was more severe in the pretreatment group compared with that of the concurrent treatment group." (PMID 26487364, 2015). "MMP-9 secretion from CAFs is suppressed by omega-3 polyunsaturated fatty acids as an anti-tumor effect." (PMID 26690480, 2015). "We further investigated the impact of tumor aggressiveness on the prognosis of Cripto-1 expression in HCC by using MMP-9 marker as an indicator for invasive potential of tumor cells." (PMID 26375669, 2015). "Specifically, activated STAT3 increases the invasive abilities of BrC cells by initiating the transcription of the MMP2 and MMP9 genes, whereas blocking STAT3 activity suppresses MMP2 and MMP9 expression, tumor invasion, and lung metastasis." (PMID 26360780, 2015). "Other investigators reported that it involved MMP-9 inhibition and strong pro-apoptotic effects against tumor cells." (PMID 26287217, 2015). "The overexpression of MMP-9 in the tumor tissue can facilitate the tumor cells to penetrate through the basilar membrane and infiltrate the adjacent tissues, resulting in tumor metastasis." (PMID 26656588, 2015). "Tumors generated using MMP9 shRNA-treated cancer cells were smaller and/or less metastatic than tumors generated with control cells, and injection of MMP9-targeted siRNA into established tumors decreased tumor growth." (PMID 25961845, 2015). "Matrix metalloproteinases (MMPs), including MMP-2 and MMP-9, facilitate the migratory or invasive potential of tumor cells by enzymatically degrading the extracellular matrix." (PMID 26155940, 2015). "Tumor-secreted MMP-9 activity is known to activate the proangiogenic factor, vascular endothelial growth factor (VEGF) and favours tumor invasion as well as tumor associated neovascularization." (PMID 26135741, 2015). "It inhibits MMP-2, MMP-3, TIMP-1, and TIMP-3 in preventing tumor angiogenesis, and MMP-9 through an autocrine loop in blocking lung and liver metastasis mediated by stromal fibroblasts." (PMID 25909283, 2015).
tumor (continued). "Cox regression analysis was performed to evaluate the correlation between tumor MMP-9 expression and clinical outcomes." (PMID 25888323, 2015). "To investigate the association between MMP-9/NGAL activity and long-term prognosis, including tumor relapse, we assessed patient status one year after surgery." (PMID 26663949, 2015). "Hesperidin (50 μM) and naringenin (25 μM), the major flavanones of Fructus aurantii, suppress TPA-induced tumor metastasis and MMP-9 transcription by inhibiting NF-κB and AP-1 activity." (PMID 26446078, 2015). "Among all members of MMPs family, MMP-2 and MMP-9 are the most concerned and their functions have been well-characterized during tumor invasive process." (PMID 26177288, 2015). "In previous studies, all types of tumor histology were included in the analysis of tumor MMP-9 expression, and the value of the prognostic factors identified in these studies is controversial." (PMID 25888323, 2015). "Many recent reports of tumor MMP-9 expression in patients with operable NSCLC have suggested that tumor MMP-9 expression is a predictor of poor prognosis." (PMID 25888323, 2015). "As assessed by the immune-reactivity scores, only MMP2 was more markedly expressed at the invasive front, whereas MMP9 was homogenously expressed throughout the invasive front and the tumor center." (PMID 26652716, 2015). "LCN2 functions to protect matrix metalloproteinase-9 (MMP-9) against degradation, which further enhances its enzymatic activity and facilitates angiogenesis and tumor growth." (PMID 25476483, 2015). "MMP9 expresses activity to degrade the extra cellular matrix (ECM) in the vicinity of tumor, which has close relationship with the invasion and metastasis of tumors." (PMID 26674531, 2015). "MMP-9 expression increases in malignant tumor tissues of various cancer types, including lung cancer, breast cancer and colon cancer." (PMID 26429875, 2015). "CHI3L1 suppressed E-cadherin but induced MMP9 and cell motility in glioma cells, all of them essential features of tumor cell invasion." (PMID 26425658, 2015). "TGF-β is also significantly correlated with MMP9 expression; MMP9 can facilitate tumor cell infiltration in lymphatic or blood systems by degrading basement membrane components." (PMID 26779375, 2015). "In an in vivo experimental model of bone metastasis, the presence of active MMP9 at the tumour-bone interface was important for bone destruction, a necessary process for tumour formation." (PMID 25605249, 2015). "MMP-9 or gelatinase B is a multidomain enzyme functioning in acute and chronic inflammatory and neoplastic diseases." (PMID 25821836, 2015). "Administration of decorin antagonized multiple receptor tyrosine kinases (e.g., Met), subsequently leading to the down-regulation of MMP-9 in the context of tumor angiogenesis." (PMID 25781946, 2015). "Following association with Smad4, the Smad complexes then translocate to the nuclei, where they activate specific target genes including MMP-9 through cooperative interactions with its DNA and other DNA-binding proteins to control tumor progression." (PMID 25940439, 2015). "Immunohistochemistry staining of tumor tissue revealed decreased expression of matrix metallopeptidase 9 (MMP-9) in mice exhibiting positive responses to MSV-EphA2 siRNA treatment." (PMID 25788424, 2015). "Matrix metalloproteinase-9 (MMP-9) plays an important role in the progression of OS by increasing tumor growth, migration, invasion, and metastasis and is associated with poor disease prognosis." (PMID 26229955, 2015). "E-cadherin exhibited low expression, whereas vimentin, MMP-2, and MMP-9 exhibited high expression in tumor cells treated with doxycycline compared with the untreated group in both the membrane and cytoplasm." (PMID 26512779, 2015). "The autocrine production of EGF-induced PTX3 altered the expression of metastatic molecules, such as increasing fibronectin and MMP-9, resulting in enhanced tumor metastasis." (PMID 25797258, 2015).
tumor (continued). "We examined tumor metastasis promoting factors (such as MMP-9, CXCR4, NF-κB) and performed western blotting analysis after 1, 7, 14, 21 and 28 days." (PMID 25884903, 2015). "MMP-7 and MMP-9 expressions can be induced in cancer cells, augmented by tumor-stromal cell interaction and possibly mediated by membrane-anchored and/or soluble factors." (PMID 25885552, 2015). "MMP9 is most likely involved in the initial degradation of the basement membrane surrounding the tumor, because MMP9 is induced under conditions that require tissue remodeling (including tumor invasion)." (PMID 25866480, 2015). "In contrast, patient 4, who had low PAI-2 and high MMP-9 IHC expression levels, experienced tumor recurrence within 9 months and died 14 months after treatment commenced." (PMID 26230665, 2015). "Accumulating evidence suggests that the upregulation of MMP-9 expression contributes to the development of tumor progression such as invasion, metastasis, and angiogenesis." (PMID 26608825, 2015). "As MMP2 and MMP9 are usually associated with tumour progression in a BSG-dependent way, we investigated their expression in a series of BASIGIN-positive human tumour cells." (PMID 26284589, 2015). "Matrix metalloproteinases (MMPs) are thought to be critical to this process and MMP-9 is considered to be the most relevant for tumor invasion." (PMID 25374279, 2015). "Accordingly, we identified suppression of effector proteins related to tumor invasion, MMP2, MMP9, and E-cadherin, in miR-124-transfected tumor cells." (PMID 25969668, 2015). "It was shown that MMP-9 induction is very important for the metastasis of different types of cancer tumor cells." (PMID 25756523, 2015). "During bone resorption, bone matrix is degraded by enzymes, such as MMP-2 and MMP-9, and the room for neoplasms growth is obtained." (PMID 25879017, 2015). "MMP inhibitors and genetic ablation of MMP-9 reduced the angiogenic switching, tumor number, and tumor growth, indicating that MMP-9 can render normal islets angiogenic." (PMID 26819959, 2015). "In tumor biology, MMP-9 plays an important role in tumor progression and it has been shown that MMP-9 increases angiogenesis, cancer cell migration and metastasis." (PMID 26219353, 2015). "In particular, MMP-2 and MMP-9 are collagenases that are crucial for tumor invasion and metastasis through degradation of collagen IV." (PMID 25927362, 2015). "TAN promote angiogenesis and metastasis in tumors by secreting protumorigenic factors, for instance; IL-8 and VEGF, potent pro-angiogenic mediators as well as MMP-9 to degrade extracellular matrix, which promote tumor growth, angiogenesis and metastasis." (PMID 26460736, 2015). "In this study, an IHC score was used to determine tumor expression levels of MMP-9, and the median IHC score was used as the cut-off value." (PMID 25888323, 2015). "Our result of 38.6% seems reasonable because it is consistent with the percentage of patients showing tumor MMP-9 positivity in previous studies (range, 29.4-68.9 %)." (PMID 25888323, 2015). "In order to take a step into the mechanism of BCYRN1’s regulating tumor cell metastasis, the RNA and protein levels of representative MMPs, namely MMP9 and MMP13, were respectively measured." (PMID 25866480, 2015). "Our data indicated that the TSP50+/p65+ or TSP50+/MMP9+ tumor were much larger than other tumors from the patients." (PMID 25811800, 2015). "Our results suggest that two circulating peptides derived from C3f, a substrate of MMP-9 in the tumor microenvironment, reflect the content of MMP-9 in tumors, and consequently indicate the therapeutic efficacy (i.e., treatment with EphA2-siRNA)." (PMID 25788424, 2015). "Only for intestinal type tumors, there was a correlation of mTOR with MMP9 expression both in the tumor center (r = 0.251, p = 0.020) and at the invasive front (r = 0.254, p = 0.018)." (PMID 26652716, 2015).